C17orf58 (chromosome 17 open reading frame 58)
Tractability: Antibody: UniProt predicts a signal peptide or a membrane-spanning region; its Gene Ontology location is reachable by antibodies, with medium confidence; the Human Protein Atlas places it where antibodies can reach.
Gene: Protein-coding gene on chromosome 17 (67,991,099 to 67,996,469, reverse strand). Ensembl gene ENSG00000186665.
Subcellular location (Human Protein Atlas): Cytosol; Plasma membrane
Gene Ontology:
Cellular component: extracellular matrix
Genetic constraint (gnomAD): Loss-of-function variants: 7 observed, 8.74 expected, observed/expected ratio (o/e) 0.8, 90% interval 0.45 to 1.49. That is too few expected variants to judge how well the gene tolerates losing a copy. Missense variants: 133 observed, 151.81 expected, observed/expected ratio (o/e) 0.88, 90% interval 0.76 to 1.01. Synonymous variants: 45 observed, 62.9 expected, observed/expected ratio (o/e) 0.72, 90% interval 0.56 to 0.92.
Homologues: Orthologues: chimpanzee C17H17orf58 (99% identical), pig C17orf58 (80% identical), mouse 1810010H24Rik (71% identical), rat C10h17orf58 (71% identical), tropical clawed frog c10h17orf58 (32% identical), chimpanzee C17H17orf58 (29% identical), macaque C16H17orf58 (28% identical).
Diseases named in the same sentence as C17orf58 in open-access papers:
C17orf58 is named in the same sentence as 1 disease in open-access papers, as found by Europe PMC text mining. Sharing a sentence is not in itself a finding about the gene and the disease. The quoted sentences say what the papers report.
breast tumors (1 paper, 2022). "In addition, amplification of C17ORF58 is reported to target genes involved in the activation of the PI3K/Akt pathway and increases the metastatic potential of breast tumors." (PMID 36685821, 2022).